HMGB1P1 (high mobility group box 1 pseudogene 1)
Description:
Binds preferentially single-stranded DNA and unwinds double-stranded DNA.
Synonyms: HMG1L7; formerly HMG1L1; HMGB1L1
Tractability: PROTAC: ubiquitination databases record sites on it.
Gene: Protein-coding gene on chromosome 20 (57,487,959 to 57,495,366, reverse strand). Ensembl gene ENSG00000124097.
Subcellular location: Nucleus; Chromosome
Subcellular location (Human Protein Atlas): Nucleoplasm
Gene Ontology:
Molecular function: damaged DNA binding; receptor ligand activity; transcription corepressor activity
Biological process: chromatin remodeling; DNA metabolic process; immune response; negative regulation of DNA-templated transcription; negative regulation of endothelial cell migration; positive regulation of autophagy; positive regulation of cell differentiation; positive regulation of chemokine production; positive regulation of endothelial cell proliferation; positive regulation of interleukin-1 production; positive regulation of interleukin-6 production; positive regulation of tumor necrosis factor production; regulation of DNA metabolic process; regulation of hemopoiesis; regulation of viral process; signal transduction
Cellular component: nucleus; chromosome; condensed chromosome
Genetic constraint (gnomAD): Loss-of-function variants: 6 observed, 8.77 expected, observed/expected ratio (o/e) 0.68, 90% interval 0.37 to 1.35. That is too few expected variants to judge how well the gene tolerates losing a copy. Missense variants: 105 observed, 145.17 expected, observed/expected ratio (o/e) 0.72, 90% interval 0.62 to 0.85. Synonymous variants: 40 observed, 53.33 expected, observed/expected ratio (o/e) 0.75, 90% interval 0.58 to 0.98.
Homologues: Orthologues: guinea pig Hmgb1 (95% identical), macaque HMGB1 (95% identical), rabbit HMGB1 (95% identical), mouse Hmgb1 (94% identical), rat Hmgb1 (94% identical), rat Hmgb1-ps34 (94% identical), rat Hmgb1l2 (93% identical), rat AABR07029613.1 (92% identical), rat Hmgb1l5 (92% identical), chimpanzee HMGB1P1 (90% identical), rat Hmgb1l1 (86% identical), tropical clawed frog hmgb1 (84% identical), and 5 more. Paralogues in human: HMGB1 (95% identical), HMGB2 (74% identical), HMGB3 (66% identical), HMGB4 (33% identical), UBTF (30% identical), SSRP1 (26% identical), TOX2 (26% identical), TOX3 (25% identical), TOX4 (24% identical), TOX (23% identical), SP100 (20% identical), HMGXB4 (20% identical), and 8 more.